PVT1 (Pvt1 oncogene)
Diseases named in the same sentence as PVT1 in open-access papers (continued):
Sharing a sentence is not in itself a finding about the gene and the disease.
cancer (continued). "In this review, we summarize the coamplification of PVT1 and MYC in cancer, the positive feedback mechanism, and the latest promoter competition mechanism of PVT1 and MYC, as well as how PVT1 participates in the downstream signaling pathway of c-Myc by regulating key molecules." (PMID 31309249, 2019). "Interestingly, CRISPRi (CRISPR-inhibition) targeting PVT1 promoter led to enhancement of MYC expression and cancer cell proliferation, while reversal of the interference abolished MYC activity." (PMID 31658672, 2019). "Both PVT1 and c-Myc are located at the same chromosomal location (8q24.21) and an increase in PVT1 expression is required for high MYC protein levels in 8q24-amplified human cancer cells." (PMID 29701689, 2018). "PVT1 is a well-known oncogenic lncRNA which is often co-amplified with the proto-oncogene MYC (MYC proto-oncogene, bHLH transcription factor) and is required for elevated MYC expression in cancer." (PMID 29702599, 2018). "At the heart of this phenomenon, there was the recently and widely studied oncogene PVT1 that switched from being the first of the hubs in the normal MMI network to fall outside the list of nodes of the cancer network." (PMID 30200360, 2018). "Another example is PVT1, a lncRNA near MYC, which is a developmental gene involved in most cancers." (PMID 30305026, 2018). "Our study provides the first evidence of the newly identified PVT1/miR-203/LASP1 axis in carcinogenesis and metastasis of ESCC and may serve as a candidate target for cancer therapy." (PMID 28404954, 2017). "As we have demonstrated that PVT1 affect the expression of the miR-203 and miR-203/LASP1 axis has been reported in various human cancers, it was thus reasonable to hypothesize that expression of LASP1 may be affected by dysregulated PVT1." (PMID 28404954, 2017). "PVT1 expression positively related to tumor size, TNM stages, lymph node metastasis and distant metastases, and served as a prognostic biomarker in different types of cancers." (PMID 29348896, 2017). "Recent studies indicated that PVT1 RNA and MYC protein expression correlated in primary human tumours, and copy number of PVT1 was co-increased in more than 98% of MYC copy number-increased cancers." (PMID 28404954, 2017). "At the heart of this phenomenon is the lncRNA PVT1 that serves as miRNA sponge in normal tissues, but not in cancer." (PMID 28187158, 2017). "Long noncoding RNA (lncRNA) PVT1 was detected all types of cancer from Cancer Genome Atlas (TCGA) project; however, the role of PVT1 in cancer is not clear." (PMID 29088881, 2017). "To investigate the role of PVT1 in ESCC progression, we detected the PVT1 expression levels in 104 paired ESCC cancer tissues and corresponding non-tumor tissues using qPCR, which was normalized to GAPDH." (PMID 28404954, 2017). "The results suggested that elevated PVT1 expression predicted a poor clinical outcome for OS in nine types of cancers (HR = 1.40, 95% CI: 1.21–1.59, P < 0.001) with no heterogeneity (I2 = 0.0%, P = 0.907)." (PMID 29348896, 2017). "Moreover, our findings highlight the role of PVT1 as biomarker for KIRC and a promising therapeutic target for cancer treatment." (PMID 27366943, 2016). "Our pan-cancer analysis revealed that kidney renal clear cell carcinoma (KIRC) shows the most extreme up-regulation of PVT1 and the strongest connection between MYC-PVT1 enrichment and clinical outcome." (PMID 27366943, 2016). "Thus, although the sample sizes of other leading cancers were small, this result implies that salivary HOTAIR and PVT1 show potential to be a novel and specific biomarker for PC." (PMID 27028998, 2016).
cancer (continued). "In line with previous reports in other epithelial cancers, PVT1 was found to be upregulated in cancer compared to noncancerous tissues and this upregulation was associated with a worse prognosis in a panel of HCC patients." (PMID 25883951, 2015). "Other lncRNAs involved in various types of cancers include HOTAIR, MEG3, PVT1 and CDKN2B-AS1." (PMID 26305674, 2015). "However, only 19 long noncoding RNAs from the LncRNADisease were found among the ESCALs, these including several lncRNAs such as HOTAIR, PVT1, H19 and GAS5 that have been reported to be dysregulated in multiple human cancers." (PMID 26158411, 2015). "Interestingly both c-MYC and PVT1 are part of the same locus known to be frequently overexpressed in cancer and c-MYC is an important oncogene known to increase cancer cell growth and proliferation." (PMID 24886442, 2014). "Additionally, they play critical roles in reprogramming the tumor immune microenvironment (TIME), influencing T cell trafficking (H19), MDSC differentiation (PVT1, RUNXOR, Lnc57Rik), Treg-mediated immunosuppression (SNHG16), and promoting immune cell-cancer cell interactions (LNMAT1, JHDM1D-AS1)." (PMID 40527978, 2025). "Accumulating evidence has shown that lncRNAs drive cancer metabolic reprogramming by directly or indirectly interacting with key metabolic enzymes and regulatory molecules, further altering related metabolites and disrupting multiple metabolic pathways, including lncRNAs H19, NBR, and PVT1." (PMID 40831535, 2025). "We also reasoned that loss of the residual PVT1ts in cells with MYC/PVT1 gain + PVT1 translocation, or cells with MYC/PVT1 gain without PVT1 translocation, would further augment MYC expression and contribute to increased aggressiveness in these cancer cells." (PMID 40027648, 2025). "Also, targeting each of HAT1, PVT1, miR-619-5p, and EZH2 individually or in combination may enhance the cancer cells’ resistance to gemcitabine and increase the effects of chemotherapy and prognosis in patients." (PMID 38559560, 2024). "The expression of PVT1 and LUCAT1 was significantly increased, and the expression of LINC00982 was significantly decreased in tumor patients, which is in line with available publications analyzing the significance of these lncRNAs not only in RCC but also in other cancers." (PMID 35441392, 2022). "Moreover, several lncRNAs that have been previously reported to be involved in various cancers as PVT1, HOTAIR, NEAT1, and MALAT1 may contribute to cancer development and progression." (PMID 33670447, 2021). "In contrast, PVT1 was highly expressed across multiple cancer types without specificity to CaP." (PMID 32059012, 2020). "Therefore, PVT1, in conjunction with or instead of MYC might be the cancer driver gene in this setting." (PMID 32877461, 2020). "Notably, several HALs, such as UCA1, PVT1, H19 and MALAT1, might adapt more than one action mode in different cancer types." (PMID 32370770, 2020). "A negative correlation dominates the relationship between PVT1 and miRNAs in cancer." (PMID 32117705, 2020). "The role of PVT1 in mediating radiation resistance, though not as extensively studied compared with drug resistance, has shown that there are numerous pathways responsible for drug resistance in cancer." (PMID 32117705, 2020). "Indeed, a recent study shows that inhibition of the PVT1 transcription does not impact on MYC expression in a cancer cell line." (PMID 32369019, 2020). "No transforming ability of PVT1 and circPVT1 per se has been demonstrated in hematopoietic cells so far, suggesting a role in tumor progression and in support of a proliferative phenotype, rather than in cancer development." (PMID 32228602, 2020). "The copy number of PVT1 exons 4A, 4B, and 9 is higher in urine samples of individuals with history of cancer in comparison to urine samples of individuals without history of cancer." (PMID 31877167, 2019).
cancer (continued). "PVT1 regulates plasminogen activator inhibitor 1 RNA-binding protein (SERBP1), plasminogen activator inhibitor-1 (PAI-1), and other molecules by competitively binding to miR-448, thereby reducing the expression of E-cadherin and promoting the invasion of cancer cells." (PMID 31380270, 2019). "Notably, a stable subline of the nontumorigenic prostate epithelial cell line overexpressing PVT1 exon 9 demonstrates increased cell proliferation, and migration, as well as in vivo malignant tumor growth and castration resistance." (PMID 31766781, 2019). "First, the cutoff values of PVT1 high expression and low expression were lack of uniform standard in different types of cancer, which may result in some heterogeneity and affect the results of the study." (PMID 30083911, 2019). "Moreover, PVT1 could also contribute to the epithelial-to-mesenchymal transition (EMT), which was required for cancer metastasis and invasion." (PMID 29088881, 2017). "However, the diagnosis effect of PVT1 is not clear in most cancers, while the expression of PVT1 has been tested in 33 type cancers of TCGA database." (PMID 29088881, 2017). "Moreover, the reported effect of PVT1 on diagnosis and detection is controversial, and no meta-anlysis has investigated the relationship between PVT1 epression and cancer diagnosis and detection." (PMID 29088881, 2017). "Notably, PVT1, SOX2‐OT and hsa‐mir‐429 were identified as common drivers in three cancer types." (PMID 28719033, 2017). "Thus, the PVT1 neighborhood in the normal-MMI-network encompasses cancer related genes as well as genes involved in mammary gland development and cell morphogenesis and the sponge program orchestrated by PVT1 results completely abolished in cancer." (PMID 25883951, 2015). "The long non-protein coding RNA (lncRNA) PVT1 has been shown to be important in cancer." (PMID 26703666, 2015). "The PVT1 (Pvt1 oncogene (non-protein coding)) gene is involved in several types of cancer." (PMID 23626673, 2013). "Additionally, PVT1 knockdown significantly inhibited cell proliferation, colony formation assay, migration, and invasion, inhibiting the expression of two matrix metalloproteinases, MMP-2, and MMP-9, suggesting that PVT1 can regulate EMT and cancer progression." (PMID 34575316, 2021). "We show that the cancer risk-associated allele of rs378854 decreases binding of the transcription factor YY1, activates in vitro expression of reporter constructs relative to the non-risk allele, and increases expression of PVT1 in primary normal human prostate tissue." (PMID 21814516, 2011). "Based on higher co-expression in malignant (n = 11) but not in benign (n = 8) nodules after surgery, MALAT1, PVT1 and HOTAIR were selected as putative cancer biomarkers to analyze 135 FNA samples." (PMID 33030666, 2021). "Salivary HOTAIR and PVT1 were not significantly elevated in BPT patients and patients with any one of eight leading cancers worldwide." (PMID 27028998, 2016). "In samples with this amplicon, MYC, PVT1 and TMEM75 do not show CNA-specific expression although the scores for MYC are suggestive (ANOVA FDR 0.02, Cancer with CNA vs. Cancer without CNA FDR 0.10, log2 ratio 0.75)." (PMID 19419571, 2009). "When the promoter of PVT1 is non-functional, the intragenic enhancers rewire it towards the promoter of MYC with a topological rearrangement in the 3D genome that boosts the oncogenic expression of MYC, thus enhancing cancer cell proliferation." (PMID 36901971, 2023). "Moreover, according to the latest promoter competition mechanism, the PVT1 promoter, as a “non-standard” tumor suppressor, is a novel candidate for designing a new therapeutic strategy for tumors in which MYC serves as a carcinoma driver." (PMID 31309249, 2019). "We found that PVT1 acts as ceRNA in the normal-MMI-network, but not in cancer." (PMID 25033876, 2014).
cancer (continued). "Of the three GBM and GSC-specific regulated lncRNAs, PVT1 and H19 have been extensively investigated for their role in cancer development and progression, whereas FAM95B1 (ENSG00000223839.7, NONHSAG052279.2, Lnc-ANKRD20A3-51) has not been explored for its role in cancer." (PMID 39302097, 2024). "Furthermore, both transient and stable overexpression of PVT1 exons 4A and 4B in a non-tumorigenic prostate epithelial cell line (RWPE1) induced increased cell proliferation and migration, which are among the hallmarks of cancer." (PMID 32358016, 2020).
tumor (380 papers, 2006 to 2026). "Elevated expression levels of PVT1 have been linked to aggressive tumor behavior, increased proliferation, and enhanced metastatic potential." (PMID 39452836, 2024). "LncRNA plasmacytoma variant translocation 1 (PVT1), located on chromosome 8q24, has been extensively validated as a tumor promoter." (PMID 37817266, 2023). "PVT1 was also linked to increased tumor metastasis, suggesting that this lncRNA plays a pro-metastasis role." (PMID 36624401, 2023). "One lincRNA called Plasmacytoma Variant Translocation-1 (PVT-1) has various impacts on tumorigenesis by downregulating tumor suppressor genes through encoding miRNAs." (PMID 36232885, 2022). "Overexpression of lncRNA PVT1 in PCa tissues and cells is associated with low overall and disease-free survival and tumor staging." (PMID 35412947, 2022). "The loss of PVT1 and miR-16-5p over-expression has been observed to drastically reduce the tumor volume in a mouse xenograft model." (PMID 36362222, 2022). "Based on the gain- and loss-of PVT1 expression, PVT1 was found to be able to evidently trigger angiogenesis within tumors, apart from enhancing tumor growth by means of modulating the STAT3/VEGFA axis in vitro and in vivo." (PMID 36249015, 2022). "We find that expression of PVT1 is regulated by tumor cells in response to cellular stress, particularly loss of cell–cell contacts and changes in matrix rigidity occurring in a YAP1-dependent manner." (PMID 35820706, 2022). "We also provided the ROC analysis of the PVT1 diagnostic potential, indicating that this lncRNA is a sufficiently discriminating biomarker capable of distinguishing between tumor and non‐tumor tissue." (PMID 35441392, 2022). "Both gain-of-function and loss-of function experiments revealed that PVT1 enhanced ccRCC cells proliferation, migration, and invasion and induced tumor angiogenesis in vitro and in vivo." (PMID 34321604, 2021). "The authors further identified a new splicing variant of PVT1, whose levels were even higher in the tumor tissue and tumor cell lines than the levels of the full-length original splicing variant and had an even higher effect on the cell proliferation." (PMID 33947142, 2021). "PVT1 deficiency curbed the tumor growth and reduced tumor weight, in contrast to mice injected with CC SIHA cells stably transfected with sh-NC." (PMID 33817293, 2021). "In a mouse xenograft model, the combination of PVT1 loss and miR-16-5p overexpression minimized tumor volume." (PMID 34336125, 2021). "Accumulating vigorous evidence indicated that lncRNA PVT1 was overexpressed in a number of cancers including GC 126, and was significantly associated with tumor disease processes 127-130." (PMID 34345204, 2021). "High PVT1 expression was significantly associated with larger tumor size (p = 0.017), higher T stage (p < 0.001), and higher N stage (p = 0.008)." (PMID 33076512, 2020). "High PVT1 expression was associated with clinicopathological markers of poor prognosis, such as larger tumour size, higher TNM stage and the presence of both lymph node and distant metastases." (PMID 32058674, 2020). "The role of PVT1 in tumor is closely associated with a variety of miRNAs and their downstream pathways." (PMID 31380270, 2019). "Overexpression of serum PVT1 was markedly associated with larger tumor size, advanced clinical stage, and accurately predicted the disease and poor prognosis." (PMID 31632195, 2019). "Higher PVT1 expression was significantly associated with higher T stage (p = 0.0369), higher N stage (p = 0.0484), and unfavorable tumor grade (p = 0.0428)." (PMID 31601234, 2019). "For example, in a tumor context where the miRNA encoded within PVT1 participate in disease progression, the use of anti-miR would be recommended." (PMID 31781490, 2019). "PVT1 encodes a cluster of five miRNA (miR-1204, miR-1205, miR-1206, miR-1207, and miR-1208) which have been shown to play both oncogenic and tumor-suppressive roles." (PMID 31781490, 2019).